RAB11A (RAB11A, member RAS oncogene family)
Diseases named in the same sentence as RAB11A in open-access papers (continued):
Sharing a sentence is not in itself a finding about the gene and the disease.
neurodevelopmental disorder (1 paper, 2025). A behavioral and cognitive disorder with onset during the developmental period that involves impaired or aberrant development of intellectual, motor, or social functions. "Our study collectively demonstrated that the RAB11A mutation c.370A>G is associated with neurodevelopmental disorders, characterized by motor deficits and brain anomalies." (PMID 40959816, 2025). "The reduced CNS area, and abnormal suggests that the rab11a deficient zebrafish model can well simulate RAB11A-related neurodevelopmental disorders." (PMID 40959816, 2025). "Recently, RAB11A mutations have been found to be associated with neurodevelopmental disorders in cohorts." (PMID 40959816, 2025). "Additionally, we have generated a rab11a deficient zebrafish model to study neurodevelopmental disorders associated with RAB11A gene mutations." (PMID 40959816, 2025). "Additionally, we have successfully developed a zebrafish model to recapitulate these neurodevelopmental disorders associated with RAB11A deficiency, offering a valuable genetic resource for further investigation into this disease." (PMID 40959816, 2025). "However, there was few animal models to study the RAB11A-NDD (RAB11A related neurodevelopmental disorders), further studies to observe phenotypes and molecular basis in animal models are required." (PMID 40959816, 2025). "RAB11A mutations have been found to be associated with neurodevelopmental disorders, but animal models are lacking for validation." (PMID 40959816, 2025). "Our findings provide new insights into RAB11A-related neurodevelopmental disorders." (PMID 40959816, 2025).
RAB11A also shares sentences with these, for which no sentence is quoted: amyotrophic lateral sclerosis (5 papers); neurological diseases (5); Parkinson disease (5); thyroid cancer (5); bladder cancer (2); Chronic Myeloid Leukemia (2); ciliopathy (2); Dengue (2); frontotemporal dementia (2); nephrotic syndrome (2); pulmonary fibrosis (2); retinal degeneration (2); Alcohol (1); Arrhythmia (1); Bardet-Biedl syndrome (1); blood disorders (1); cardiac arrest (1); Charcot-Marie-Tooth disease type 4C (1); Chlamydia pneumonia (1); chlamydial infection (1); Cholestatic liver disease (1); cholesterol metabolism disorder (1); chronic hepatitis (1); chronic kidney disease (1); CMV infection (1); colon adenocarcinoma (1); colorectal tumors (1); COVID-19 (1); demyelinating peripheral neuropathy (1); depression (1).
A further 37 diseases each share a sentence with RAB11A in 1 paper.